ABCB1 (ATP binding cassette subfamily B member 1)
Diseases named in the same sentence as ABCB1 in open-access papers (continued):
Sharing a sentence is not in itself a finding about the gene and the disease.
ovarian carcinoma (continued). "Of equal importance, other ABC transporters beyond ABCB1 may also be overexpressed in ovarian cancer cells and contribute to chemoresistance." (PMID 41303640, 2025). "For example, in ovarian cancer cells, ABCB1 expression may be regulated by transcription factors such as forkhead box protein P1 (FOXP1), or through hormonal modulation by estrogen and progesterone." (PMID 41303640, 2025). "erastin can therefore reverse ABCB1-mediated docetaxel resistance in ovarian cancer." (PMID 38469234, 2024). "In addition, a recent study revealed that overexpressing ABCB1 in ovarian cancer cell lines promoted resistance to niraparib." (PMID 38236558, 2024). "Erastin is involved in reversal of ABCB1-induced docetaxel resistance in ovarian cancer." (PMID 38469234, 2024). "An interesting study found that cotreatment with erastin and docetaxel significantly decreased cell viability, promoted cell apoptosis and induced cell cycle arrest at the G2/M stage in docetaxel-resistant ovarian cancer (A2780/Taxol) cells (which overexpress the ABCB1 protein)." (PMID 38203758, 2024). "In addition, the ABCB1-overexpressing NCI-ADR-RES human ovarian cancer cells were resistant to HS-173 (RF = 9) as compared to the parental OVCAR-8 cancer cells." (PMID 37048130, 2023). "Indeed, ABCB1 expression was shown to be correlated with resistance to olaparib and rucaparib in ovarian cancer cell lines." (PMID 37430137, 2023). "Even between ovarian cancer cell lines, evidence exists for both Gli1 and Gli2-driven mechanisms, and it is unclear whether one or both are required for expression of ABCB1." (PMID 37954979, 2023). "In this study, we demonstrate that aberrant regulation of the Ca2+-mediated CAMKIID/CREB1 pathway contributes to ABCB1 over-expression and MDR creation and that CAMKIID and CREB1 are attractive targets for restoring doxorubicin efficacy in ABCB1-mediated MDR ovarian cancer." (PMID 36439493, 2022). "We questioned whether terfenadine impacts the expression or function of ABCB1 in these MDR ovarian cancer cells, as ABCB1 overexpression was essential for the chemoresistance of A2780-ADR." (PMID 36439493, 2022). "Studies have shown that ABCB1 expression is a prognostic factor in ovarian cancer." (PMID 36551731, 2022). "This reverses docetaxel resistance in ABCB1-overexpressing ovarian cancer cells." (PMID 35775079, 2022). "A preclinical study has found that erastin can reverse ABCB1-mediated resistance to docetaxel in ovarian cancer, indicating that the combination of erastin and docetaxel is a promising strategy available to chemotherapy-resistant patients with ovarian cancer." (PMID 35847022, 2022). "Interestingly, acquired resistance to olaparib in ovarian cancer cell lines has been reported to occur via upregulation of MDR‐1, the protein encoded by ABCB1." (PMID 35708734, 2022). "Human ovarian cancer cell lines OVCAR3, A2780, A2780/DDP and A2780/Taxol were exposed to paclitaxel or cisplatin transfected with or without miR-186, and miR-186 was found to induce sensitivity of ovarian cancer cells to paclitaxel and cisplatin by targeting ABCB1." (PMID 36439168, 2022). "Downregulation of Jagged1 in drug resistant ovarian cancer cell line SKOV3TRip2 did not alter ABCB1 mRNA, but resulted in diminished GLI2 (Glioma-associated oncogene homolog 2), although not GLI1." (PMID 35582031, 2021).
ovarian carcinoma (continued). "Regardless, our new ovarian cancer organoid cell lines are providing a clinically relevant validation of the link between ABCB1 upregulation and paclitaxel resistance in ovarian cancer, consistent with previously established immortalized human cell lines in the laboratory setting." (PMID 34347777, 2021). "Demonstration of clinical relevance for ABCB1 upregulation on chemoresistance in ovarian cancer has been inconsistent; however, recent reports highlight the importance of ABCB1-overexpression in the treatment of recurrent ovarian cancer." (PMID 34347777, 2021). "We have also shown for the first time in ovarian cancer cells that poziotinib, currently in late phase clinical trials for patients with NSCLC and an ERBB2 exon 20 insertion mutation, has a similar effect when combined with paclitaxel in ABCB1-overexpressing ovarian cancer cells." (PMID 34347777, 2021). "The ABCB1-overexpressing multidrug-resistant KB-V-1 human epidermal cancer cells, NCI-ADR-RES human ovarian cancer cells, ABCB1-transfected MDR19-HEK293 cells, and the corresponding drug-sensitive parental KB-3-1, OVCAR-8, and pcDNA-HEK293 cells are equally sensitive to erdafitinib treatment." (PMID 32466597, 2020). "High expression levels may be an intrinsic feature of the cell type, or due to promoter translocations between ABCB1 and genes with strong constitutive expression, such as those found in patients with breast or ovarian cancer who relapse after prior therapy." (PMID 31770110, 2020). "ABCB1 fusions have been proposed as a mechanism of upregulation and were found in approximately two-thirds of breast and ovarian cancer patients who had received three or more lines of paclitaxel and 26% of patients who received at least one line of liposomal doxorubicin." (PMID 32403357, 2020). "In summary, our results demonstrated that erastin could reverse ABCB1-mediated docetaxel resistance in ovarian cancer, suggesting that the combination of erastin and docetaxel may expand the limited options for chemo-resistant ovarian cancers." (PMID 31921655, 2019). "Thus, the authors revealed an interesting regulatory axis UCA1/miR-129/ABCB1 that sensitizes ovarian cancer cells to paclitaxel." (PMID 35582590, 2019). "Notably, a previous study revealed that, although reduced ABCB1 expression levels in epithelial ovarian cancer were related to longer progression-free survival of patients, the role of P-glycoprotein in epithelial ovarian cancer is uncertain." (PMID 30131693, 2018). "However, the exact role of ABCB4transporter in MDR is still unclear, as silencing of ABCB4 did notrestore sensitivity whereas silencing of ABCB1 completely restoredsensitivity in taxane-resistant ovarian cancer cell line." (PMID 31223218, 2018). "In support of this notion, afatinib reversed ABCB1-mediated multidrug resistance in ABCB1-overexpressing ovarian cancer cells by inhibiting the efflux function of ABCB1 and GW8510, a cyclin-dependent kinase inhibitor, inhibited RRM2 expression through promoting its proteasomal degradation." (PMID 29765556, 2018). "In agreement with the situation in research on other solid tumors (e.g., ovarian cancer), it may be concluded that single genes and protein products as ABCB1, ABCC1, and ABCG2 connected with chemoresistance are well characterized also in EC." (PMID 29543757, 2018). "In addition, afatinib reversed ABCB1-mediated multidrug resistance in ABCB1-overexpressing ovarian cancer cells by inhibiting the efflux function of ABCB1." (PMID 29765556, 2018). "ABCB1 has been reported to contribute to the SP phenotype of ovarian cancer cells." (PMID 28297580, 2017). "Our results are the first to demonstrate that miR-186 may sensitize ovarian cancer cell to paclitaxel and cisplatin by targeting ABCB1 and modulating the expression of GST-π." (PMID 26626440, 2015). "Taken together, these results indicated that afatinib could reverse the MDR to ABCB1 substrate drugs in ABCB1-overexpressing ovarian cancer cells." (PMID 26317651, 2015).
ovarian carcinoma (continued). "In conclusion, we demonstrated for the first time that miR-186 overexpression may increase the sensitivity of ovarian cancer cells to paclitaxel and cisplatin by targeting ABCB1 and modulating GST-π." (PMID 26626440, 2015). "Ours is the first study to demonstrate that miR-186 overexpression may increase the sensitivity of ovarian cancer cells to paclitaxel by targeting ABCB1 and modulating GST-π." (PMID 26626440, 2015). "Therefore, it is of vital medical significance to overcome or reverse ABCB1-mediated MDR in patients with ovarian cancer." (PMID 26317651, 2015). "However, ∼80% of ovarian cancer cases are diagnosed at an advanced stage and these patients are intrinsically resistant to chemotherapy mainly due to ABCB1-mediated MDR." (PMID 26317651, 2015). "In a model for ovarian cancer, drug resistance was reverted after downregulation of ABCB1 by shRNA." (PMID 24069258, 2013). "Thus, erastin could reverse ABCB1-mediated docetaxel resistance in ovarian cancer and improve chemotherapy efficiency in these patients." (PMID 38203758, 2024). "Moreover, ABCB1 overexpression determines Olaparib resistance in ovarian cancer patients." (PMID 39090086, 2024). "C-MET enhances chemoresistance of human ovarian cancer cells, while the CDKN2A (p16) gene is a candidate for the tumor-suppressor gene, N-cadherin protein increases cell metastatic capacity, and finally P-glycoprotein/ABCB1 encodes drug transporter systems and activates multi-drug resistance." (PMID 38248100, 2023). "Ferroptosis induced by erastin may reverse ABCB1-mediated docetaxel resistance in ovarian cancer." (PMID 35903347, 2022). "DO analysis revealed that DEGs PSAT1, FOLR1, ABCB1, SFRP1, SFRP1, BUB1B have a greater association with female reproductive system tumor-related diseases, such as malignant ovarian surface epithelial-mesenchymal tumor, ovarian epithelial carcinoma, and ovarian cancer." (PMID 35719392, 2022). "Interestingly, resistance may be overcome by ABCB1 inhibitors (verapamil and elacridar), which can be used against drug resistance mediated by ABCB1, in ovarian cancer treated by olaparib and paclitaxel." (PMID 35873570, 2022). "Moreover, EVs carrying the P-glycoprotein (P-gp, also called MDR-1 or ABCB1) drug efflux pump mediated the transfer of multidrug resistance to sensitive cells in many human cancer models, including prostate and ovarian cancers, acute T lymphoblastic leukemia, and osteosarcoma." (PMID 32150875, 2020). "In ABCB1 deficient taxol-resistant A549 cancer cells, Cav-1 upregulation was observed and Cav-1 overexpression correlated with little ABCB1 protein expression in human ovarian cancer cells, and ABCB1 overexpression was not localized in caveolae." (PMID 26431273, 2015). "In ovarian cancer, one study reported that SORL1 can stabilize ATP-binding cassette subfamily member 1 (ABCB1, also known as multidrug resistance protein 1 or MDR1) to enhance resistance to cisplatin." (PMID 39858026, 2025). "Efflux of payloads by ATP-binding cassette (ABC) transporters such as ABCB1 (P-glycoprotein) and ABCC1 (MRP1) is another resistance mechanism, particularly in chemotherapy-pretreated ovarian cancers." (PMID 41357243, 2025). "Overexpression ABCB1, FGF2, CXCR4, and IL6 portends aggressive ovarian cancer behaviors and poor prognoses." (PMID 40507922, 2025). "Synergy was observed for the combination of docetaxel and ritonavir in ovarian cancer cell lines 899 and NCI-ADR-RES that have relatively high expression of ABCB1." (PMID 38318527, 2024). "In both olaparib- and paclitaxel-treated ovarian cancer cells, verapamil and elacridar MDR1 inhibitors can reverse ABCB1-mediated drug resistance, but the clinical trial outcome is poor." (PMID 37190285, 2023). "After computational prediction of the miR-186 binding site in 3’UTR of ABCB1, the mechanism of miR-186-mediated sensitivity to PTX was evaluated in in vitro models of ovarian cancer." (PMID 37842231, 2023).
ovarian carcinoma (continued). "Epithelial ovarian cancer tissues have been shown to express other ABC transporters including, ABCC3 (MRP3), ABCC4 (MRP4), ABCB1 as well as other membrane transporters." (PMID 37838788, 2023). "In a preclinical study, the reduction of ABCB1 and BCL-2 proteins via codelivery of siABCB1 and siBCL2, respectively, sensitized paclitaxel- and cisplatin-resistant SKOV3 and A2780 ovarian cancer cells to therapeutics." (PMID 36551731, 2022). "As a result, additional research into miRNA-induced ABCB1 or ABCG2 expression, which results in ovarian cancer drug resistance, will aid in our knowledge of the mechanism of drug resistance of ABC transporters." (PMID 35799305, 2022). "Our previous study showed that hypoxia-induced NOTCH and HIF-1α elevated SOX2 expression to promote sphere formation and drug resistance by increasing ALDH1, ATP-Binding Cassette Subfamily B Member 1 (ABCB1), and ABCG2 expression in ovarian cancer cells." (PMID 34064635, 2021). "Among the various ABC transporters, ABCB1 (MDR1) and ABCB4 (MDR3) are thought to play important roles in ovarian cancer." (PMID 34504843, 2021). "The inhibition of Gli1 expression decreases ABCB1 and ABCG2 gene expression levels, thus enhancing the response of ovarian cancer cells to certain chemotherapeutic drugs." (PMID 33968932, 2021). "This study investigated the relationship of the five ABC transporters ABCA1, ABCB1, ABCB3 (also known as TAP2), ABCC2 and ABCG2 with ovarian cancer chemoresistance and outcome." (PMID 35582032, 2021). "Consequently, erastin can reverse ABCB1-mediated docetaxel resistance in ovarian cancer, revealing that the combination of erastin and docetaxel may potentially offer an effective administration for chemo-resistant patients suffering from ovarian cancers." (PMID 31921655, 2019). "Expression of ABCB1 and ABCG2 correlates with resistance to cisplatin and paclitaxel in ovarian cancer cell lines (2008, KF28, TU-OM-1, OVCAR3, SKOV3) and in cells from patient and mouse ascites." (PMID 30042330, 2018). "In ovarian cancer chemoresistance, the most commonly targeted of these transporters are the ABCB subfamily, with multidrug resistance protein 1 (MDR1, also known as P-glycoprotein (P-gp) and ABCB1) being the most exhaustively studied." (PMID 29057791, 2017). "Inhibition of Gli1 decreases ABCB1 and ABCG2 gene expression in ovarian cancer and enhances ovarian cancer-specific chemotherapeutic response." (PMID 29117122, 2017). "It was found that the inhibition of Gli1 expression can decrease ABCB1 and ABCG2 gene expression levels and enhance the response of ovarian cancer cells to specific chemotherapeutics." (PMID 26649310, 2015). "It was recently found that abnormal expression of the hedgehog (Hh) signaling pathway transcription factor Gli1 is involved in the regulation of ABC transporters ABCB1 and ABCG2 in ovarian cancer." (PMID 26649310, 2015). "The drug-resistance-related genes ABCB1, ABCC1 GSK3A, had significantly higher expression levels in OCICs than in primary ovarian cancer cells." (PMID 25369529, 2014). "The co-localization of CD44 with ABCB1 and ABCC2 in ovarian cancer tissues suggests a functional link between CD44 expression and chemoresistance." (PMID 24124770, 2013). "An overlapping set of seven genes (ABCB1, APC, BRCA1, CDH1, DNAJC15, HIC1 and SULF2) displayed the same methylation changes in the examined set of ovarian carcinoma cell lines." (PMID 20544021, 2010). "We have analyzed the relationship between CYLD and ABCB1 levels in ovarian cancer samples, and found a significant negative correlation between the expression levels of ABCB1 and levels of CYLD." (PMID 40012003, 2025). "Our findings identify novel HER3/CYLD/ABCB1 axis that regulate tumor growth and DDP resistance, which may be used as potential novel therapeutic target(s) to overcome ovarian cancer DDP resistance." (PMID 40012003, 2025).
ovarian carcinoma (continued). "Interestingly, our findings suggest that engineered exosomes are more efficient at delivering ABCB1 siRNA into tumor cells to function and, in combination with DDP, can treat drug-resistant ovarian cancer." (PMID 41306963, 2025). "For instance, hypermethylation of ABCB1 and demethylation of the ABCG2 promoter may affect therapeutic efficacy and lead to chemoresistance in ovarian carcinoma, effects attributed to upregulation of P-gp." (PMID 38539161, 2024). "A study using the non-HGSOC ovarian cancer cell line A2780, showed that treatment with erastin together with docetaxel resulted in increased apoptosis in ABCB1 over-expressing A2780 cells." (PMID 37838788, 2023). "This is not unexpected since patients with recurrent ovarian cancer have already received paclitaxel, an ABCB1 substrate, as part of their primary therapy." (PMID 34347777, 2021). "Likewise, Hedgehog signaling directly regulates the expression of ABCB1 and ABCG2 in ovarian cancer." (PMID 33968932, 2021). "Although lapatinib shows the highest degree of synergy with paclitaxel in our study, the possibility that other untested agents are more effective than lapatinib in ABCB1-overexpressing ovarian cancers cannot be ruled out." (PMID 34347777, 2021). "The trials did not select patients by ABC transporter expression, and clinical trials targeted ABCB1 and ABCG2 (with only a few targeting ABCC2), but other ABC transporters also likely to play important roles in ovarian cancer progression and chemotherapy resistance." (PMID 35582032, 2021). "Therefore, more studies on the miRNA-induced ABCB1 or ABCG2 expression, which leads to drug resistance in ovarian cancer, will improve our understanding of the drug resistance mechanism of ABC transporters." (PMID 34660304, 2021). "Our data indicate that, in addition to ABCB1, other transporters, especially those in the ABC1 family of transporters, may be playing an important role in the ovarian cancer response to chemotherapy treatment." (PMID 31052165, 2019). "In ovarian cancer, a common mechanism for resistance to the taxane paclitaxel and other chemotherapy agents is overexpression of ATP-dependent efflux pumps, especially Multidrug Resistance Protein 1 (MDR1)/P-glycoprotein/ABCB1." (PMID 29963013, 2018). "In ovarian cancer cells isolated for the SP, Notch pathway genes (FPTG, ST3GAL6, and ADAM19), stem cell markers NANOG and OCT4, and three ABC transporter genes (ABCG2 [both lines], ABCC4 [SKOV3 only], and ABCB1 [A224 only]) were induced." (PMID 30042330, 2018). "ABCB1 expression is uncommon in ovarian cancers in the clinical setting so we investigated non-MDR mechanisms of resistance to taxanes." (PMID 28399108, 2017). "For the whole group of ovarian cancer patients the polymorphic variants in PGR, ABCB1, GSTT1, GSTM1 and GSTP1 genes did not change the risk of developing cancer." (PMID 25591549, 2015). "Based on these findings and our study results, we consider that miR-186 may inhibit the development of drug resistance by targeting ABCB1 and regulating GST-π expression in ovarian cancer cells." (PMID 26626440, 2015). "Herein, afatinib at nontoxic concentrations significantly reversed ABCB1-mediated MDR in ovarian cancer cells in vitro (p < 0.05)." (PMID 26317651, 2015). "HA (5 μg/ml) did not induce ABCB1 expression in any of the ovarian cancer cell lines used in this study (data not shown)." (PMID 24124770, 2013). "Integrative bioinformatics of cisplatin-treated ovarian cancer datasets from the Gene Expression Omnibus (n=255) identified six molecular drivers of resistance: Kaiso (ZBTB33), pregnane X receptor (PXR), NF-κB, HER2 (ERBB2), P-glycoprotein (P-gp/ABCB1), and HIF1A." (PMID 41438580, 2026).